MALAT1 (metastasis associated lung adenocarcinoma transcript 1)
Diseases named in the same sentence as MALAT1 in open-access papers (continued):
Sharing a sentence is not in itself a finding about the gene and the disease.
gastric cancer (continued). "We found 3 novel lncRNAs in the top 20 (FRGCA at 3, MALAT1 at 13 and MEG3 at 20) that were recently associated with gastric cancer." (PMID 27992375, 2017). "In summary, we found that deregulation of MALAT1 is involved in carcinogenesis and metastasis of gastric cancer." (PMID 28077118, 2017). "Recent research has revealed that MALAT1 play pivotal roles in tumorigenesis of cancers including gastric cancer." (PMID 28396617, 2017). "The expression of MALAT1 was significantly elevated in various gastric cancer cell lines and gastric cancer tissues compared to normal cell lines and tissues (p < 0.01)." (PMID 28077118, 2017). "MALAT1 was found to be highly expressed in gastric cancer cells and probably promoted GC cell proliferation partly by regulating SF2/ASF." (PMID 27992375, 2017). "In our study, we have demonstrated that lncRNA MALAT1 regulates proliferation and metastasis in gastric cancer cells." (PMID 28077118, 2017). "We also investigated the clinical significance of MALAT1 level as a predictor of severity of clinicopathological factors in patients with gastric cancer, and tried to dissect MALAT1’s molecular mechanisms with respect to invasion and metastasis in vitro." (PMID 28077118, 2017). "We present here the novel finding that MALAT1 is increased in gastric cancer tissues compared to normal tissues according to microarray analysis." (PMID 28077118, 2017). "To study the biological function of MALAT1 in gastric cancers, we investigated the effect of MALAT1 knockdown on cell proliferation and cell cycle progression in gastric cancer cells." (PMID 27486823, 2016). "Our unpublished data indicated that the expression IGF-1R, a target of miR-122 was positively correlated with the expression of MALAT1 in gastric cancer cell lines." (PMID 27486823, 2016). "The results showed that MALAT1 was expressed in all the 6 cell lines, and significantly over-expressed in poorly differentiated gastric cancer cell lines, including MKN45, CTC141 and CTC105." (PMID 27486823, 2016). "Here, we reported that the tissue and plasma MALAT1 levels were significantly higher in gastric cancer patients with distant metastasis (P<0.01) than patients without distant metastasis and the healthy controls." (PMID 27486823, 2016). "The expression of MALAT1 in the four gastric cancer cell lines (SNU620, SNU005, SNU016, and AGS) was increased by 5-Aza-dC treatment." (PMID 27016420, 2016). "The miR-122-IGF-1R signaling correlated with the deregulated MALAT1 expression in gastric cancer cells." (PMID 27486823, 2016). "To verify the functional roles of exosomal MALAT1 from M2‐polarized macrophages, we collected exosomes from M2‐polarized macrophages transfected with si‐Ctrl (SI‐NC) and si‐MALAT1 (SI‐M1 and SI‐M2), and used them to treat gastric cancer cells." (PMID 38639382, 2024). "We confirmed that M2‐EX treatment led to an upregulation of MALAT1 in gastric cancer cells." (PMID 38639382, 2024). "Finally, a dual‐targeted inhibition of MALAT1 in both gastric cancer cells and macrophages by exosome‐mediated delivery of siRNA remarkably suppressed gastric cancer growth and improved chemosensitivity in mouse tumor models." (PMID 38639382, 2024). "Furthermore, the enhancement of glucose uptake, lactate production, ATP level, and LDH activity in gastric cancer cells by M2‐EX was abolished by MALAT1 knockdown." (PMID 38639382, 2024). "Moreover, the MALAT1/miR-204/LC3B signaling pathway plays a crucial role in H. pylori-induced gastric cancer and is involved in the regulation of autophagy during infection." (PMID 37588204, 2024). "The results of protein stability assay showed that the low levels of δ‐catenin in gastric cancer cells treated with si‐MALAT1 M2‐EX could be rescued by MG‐132 treatment, indicating that MALAT1 may maintain δ‐catenin protein stability in gastric cancer cells." (PMID 38639382, 2024).
gastric cancer (continued). "We observed an increase in MALAT1 expression in gastric cancer tissues compared to normal tissues as well as a moderate positive correlation between CD163 (an indicator of TAM infiltration in tumors) and HIF‐1α gene expression (but not δ‐catenin) in gastric cancer tissues by analyzing TCGA data." (PMID 38639382, 2024). "The intensive presence of Cy3‐labeled MALAT1 signals in gastric cancer cells indicated that MALAT1 could be transmitted from M2‐polarized macrophages to gastric cancer cells via exosomes." (PMID 38639382, 2024). "Curcumin targets H19 in gastric cancer cells and Malat1 in colon cancer cells." (PMID 37796408, 2023). "According to our studies, MALAT1 is a hub microRNA among others in gastric cancer." (PMID 35650297, 2022). "Similarly, MALAT1 was found to enhance the proliferation ability of gastric cancer cells by inhibiting the expression of a set of miRNAs including miR-202." (PMID 35682549, 2022). "In gastric cancer, MALAT1 RNA level was more than normal tissue." (PMID 34308750, 2021). "In the plasma for gastric cancer patients, MALAT1 RNA level was higher than controls and might be applied to prognosis." (PMID 34308750, 2021). "Moreover, MALAT1 abrogated the inhibitory effect of H2 gas on the migration of MGC-803 gastric cancer cells (p < 0.01 for MALAT1 + H2 vs. MALAT1 and MALAT1 + H2 vs. H2)." (PMID 33482814, 2021). "The expression of UPF1 is negatively correlated with the expression of MALAT1 in gastric cancer." (PMID 33732285, 2021). "This study demonstrated the efficacy of molecular hydrogen in inhibiting the growth of gastric cancer by reducing the proliferation and migration of gastric cancer cells, which was through downregulating lncRNA MALAT1 and polycomb-group family member EZH2 and upregulating miR-124-3p." (PMID 33482814, 2021). "MALAT1 is upregulated in a variety of tumors, including gastric cancer." (PMID 33732285, 2021). "Moreover, CCL21-mediated activation of the MALAT1/SRSF1/mTOR axis underpins the development of gastric carcinoma." (PMID 34421979, 2021). "LncRNA MALAT1 strengthens cell stemness in gastric cancer by enhancing the mRNA stability of SOX2." (PMID 32239639, 2020). "Though a growing number of long noncoding RNAs (lncRNAs), including HOTAIR, MEG3, MALAT1, H19, GAPLINC, and GClnc1, have been reported to be associated with gastric cancer tumorigenesis, the role of lncRNAs in human gastric cancer and their prognostic value are still inadequately explored." (PMID 32117443, 2020). "MALAT1 induced CDDP resistance by enhancing autophagy in gastric cancer cells, which could be reversed by miR-30b overexpression." (PMID 33050642, 2020). "Functional experiments revealed that MALAT1 can regulate expression of classical VM markers, such as VE-cadherin, β-catenin, MMP-2/9, MT1-MMP, p-ERK, p-FAK and p-paxillin, and MALAT1, whose levels were also associated with OS in stage gastric cancer patients." (PMID 32169087, 2020). "Furthermore, MALAT1 plasma expression was higher in patients with gastric cancer compared with healthy controls and had prognostic and diagnostic value." (PMID 33333725, 2020). "Therefore, the activation of autophagy becomes a novel molecular mechanism for chemoresistance modulated by some lncRNAs in cancer cells, such as GBCDRlnc1 in gallbladder cancer and MALAT1 in gastric cancer." (PMID 33050642, 2020). "It is suggested that a high level of MALAT1 could be a potential biomarker for distant metastasis of gastric cancer." (PMID 31572428, 2019). "For instance, increased serum MALAT1 indicated a poor prognosis in gastric cancer." (PMID 30337839, 2018). "MALAT1 is elevated in the whole blood of metastatic lung cancer patients, and HULC, detected in the blood, is also proposed as a diagnostic biomarker both for liver cancer and gastric cancer." (PMID 29416704, 2018).
gastric cancer (continued). "Additionally, MALAT1 has been demonstrated to enhance cell motility of lung adenocarcinoma cells and promote the migration and invasion of gastric cancer cells via EMT." (PMID 30285605, 2018). "MALAT1 expression has been observed to be correlated with peritoneal dispersion in gastric cancer suggesting that tumors with MALAT1 might be on the verge of metastatic progression." (PMID 29719612, 2018). "There is a wealth of evidences about MALAT1 overexpression in gastric cancer (GC)." (PMID 29739426, 2018). "In our study, we found that deregulation of MALAT1 could be involved in both tumorigenesis and invasiveness in gastric cancer cells." (PMID 28077118, 2017). "MALAT1 levels were measured in 47 of 50 patients with gastric cancer." (PMID 28077118, 2017). "Furthermore, we found high enrichment of H3K27Ac in gastric cancer tissues compared with normal tissues at the promoter of MALAT1." (PMID 29162158, 2017). "We speculate that histone acetylation activation might contribute to the upregulation of MALAT1 in gastric cancer tissues." (PMID 29162158, 2017). "The MALAT1/miR-1297/HMGB2 regulator pathway provided a novel therapeutic method for gastric cancer." (PMID 28396617, 2017). "So our preliminary data combined with several recent studies suggested that the miR-122-IGF-1R axis might participate in the MALAT1 dysregulation in gastric cancer." (PMID 27486823, 2016). "Next, we performed Q-PCR to examine the expression of MALAT1 in gastric cancer cell lines." (PMID 27486823, 2016). "To investigate whether MALAT1 facilitates gastric cancer cell migration and invasion, we evaluated cancer cell migration through transwell and invasion through matrigel." (PMID 27486823, 2016). "Knock-down MALAT1 could inhibit the expression of N-cadherin, CyclinD1 and Bcl-xl, which might explain why knock-down MALAT1 could significantly inhibit cell proliferation and invasion in gastric cancer cells (Supple." (PMID 27486823, 2016). "We then investigated whether miR-122 could inhibit the expression of MALAT1 in gastric cancer cells." (PMID 27486823, 2016). "Two individual MALAT1 siRNAs were transfected into the two gastric cancer cell lines respectively." (PMID 27486823, 2016). "Functional studies revealed that knockdown of MALAT1 could inhibit cell proliferation, cell cycle progression, migration and invasion, and promote apoptosis in gastric cancer cells." (PMID 27486823, 2016). "To verify whether 5-Aza-dC influences MALAT1 expression, we treated four gastric cancer cell lines with 5-Aza-dC." (PMID 27016420, 2016). "Furthermore, the miR-122-IGF-1R signaling correlated with the dysregulated MALAT1 expression in gastric cancer." (PMID 27486823, 2016). "Knockdown MALAT1 significantly inhibited the malignant behaviors of gastric cancer cells." (PMID 27486823, 2016). "In addition, high levels of plasma MALAT1 independently correlated to a poor prognosis for gastric cancer patients (hazard ratio, 0.242; 95% CI, 0.154-0.836; P=0.036; Cox regression analysis)." (PMID 27486823, 2016). "The association between MALAT1 (5th in the prediction results) and gastric cancer has also been confirmed by experimental observations that MALAT1 was frequently upregulated in gastric cancer cell lines and could induce gastric cancer cell proliferation." (PMID 26577439, 2015). "In addition, up-frameshift protein 1(UPF1) may regulate MALAT1, and the UPF1/MALAT1 pathways might potentially serve as a promising area of therapeutic exploration for the treatment of gastric cancer." (PMID 39346921, 2024). "In gastric cancer (GC), the ARlncRNA MALAT1 intensifies cisplatin resistance through the stimulation of autophagy, by down-regulating miR-30b and concomitantly up-regulating ATG5." (PMID 37588204, 2024). "Likewise, MALAT1 can be a powerful candidate for prognostic goals in gastric cancer." (PMID 35650297, 2022).
gastric cancer (continued). "Amounting evidence indicated that the MALAT1 was highly expressed in various types of cancer, including ovarian cancer, gastric cancer (GC), colorectal cancer, papillary thyroid cancer, and non-small cell lung cancer." (PMID 34222668, 2021). "LncRNA MALAT1 could function as a sponge RNA of miR-23b-3p and conferred chemoresistance of gastric cancer cells through attenuating the inhibitory effects of miR-23b-3p on expression of autophagy related 12 (ATG12) and promote autophagy of gastric cancer cells." (PMID 32192494, 2020). "In gastric cancer, MALAT1 could drive the development of cancer and promote peritoneal metastasis." (PMID 31792655, 2020). "In gastric cancer, MALAT1 wasreported to promote tumorigenicity and metastasis throughfacilitating vasculogenic mimicry and angiogenesis.In triple-negative breast cancer, MALAT1 was found topromote cell proliferation and invasion via decreasingexpression of miR-129-5p." (PMID 31863664, 2020). "Furthermore, under propofol and cisplatin treatment, the inhibitory effect on tumour growth of gastric cancer xenograft was strengthened by downregulation of MALAT1 and ATG5 expression, which might be partly achieved via inhibition of autophagy." (PMID 32596964, 2020). "Mechanically, it has been demonstrated that the level of MALAT1 was lower and miR‐30e was upregulated, which caused suppression of autophagy‐related genes 5 (ATG5), and subsequently inactivated autophagy‐related chemoresistance in gastric cancer cells following propofol treatment." (PMID 32596964, 2020). "It has been reported that MALAT1 associates with EZH2 and enhanced methylation of H3K27 to downregulate genes in renal cancer cells; on the other hand, MALAT1 upregulates EGFL7 by altering the level of H3 histone acetylation at EGFL7 promoter in gastric cancer." (PMID 29511340, 2018). "Bioinformatics analysis with starbase v2.0 revealed that MALAT1 formed complementary base pairing (two putative 7-mer complementary sequences) with miR-23b-3p, which has been shown to target ATG12 and regulates autophagy-associated chemoresistance in gastric cancer in the previous study." (PMID 29162158, 2017). "Taken together, these results demonstrated that MALAT1/miR-1297/HMGB2 axis acted as critical regulator pathway in GC tumorigenesis and progression, which provided a novel therapeutic target for gastric cancer." (PMID 28396617, 2017). "Consequently, lncRNA MALAT1 could be a new biomarker that being therapeutic target for diagnosis of gastric cancer." (PMID 28077118, 2017). "Thus, our results indicated that intervention of MALAT1/miR-1297/HMGB2 regulator pathway could inhibit gastric cancer progression." (PMID 28396617, 2017). "Moreover, down-regulation of MALAT1 promoted apoptosis in the two gastric cancer cell lines." (PMID 27486823, 2016). "So we test whether miR-122 could regulate the MALAT1 level in gastric cancer cells." (PMID 27486823, 2016). "However, little is known about the role of MALAT1 in gastric cancer." (PMID 27486823, 2016). "Next, we systematically examined the MALAT1 levels in the plasma of 36 healthy controls (HC) and 72 gastric cancer patients, including 36 GC/NDM and 36 GC/DM." (PMID 27486823, 2016). "In agreement, MALAT1 knockdown in BGC823 and SGC901 gastric cancer cells reduces migration, invasion, VM formation, and angiogenesis." (PMID 40277941, 2025). "Zinc mainly contributes to gastric cancer cell resistance through zinc finger proteins such as ZFP64, GLI1, ZFP91, ZNF139, which regulate gastric cancer cell resistance through pathways such as GAL-1, MALAT1, AKT-mTOR, or by modulating miRNA." (PMID 38370477, 2024). "In conclusion, we identified that M2 TAMs secreted exosomes to transmit MALAT1 to gastric cancer cells, in which MALAT1 stabilized the δ‐catenin protein and upregulated HIF‐1α expression, leading to enhanced glycolysis and gastric cancer progression." (PMID 38639382, 2024).
gastric cancer (continued). "Referring to MALAT1, other studies show that RSV inhibits proliferation and the migration and invasion of human cells in gastric cancer, e.g. through the MALAT1/miR-383-5p/DDIT4 signaling pathway in the SGC7901 cell line." (PMID 39795061, 2024). "M2 TAMs performed these effects via the release of exosomes that contained a high level of lncRNA MALAT1, which stabilized the δ‐catenin protein through lncRNA‐protein interaction and upregulated HIF‐1α via the ceRNA network in gastric cancer cells." (PMID 38639382, 2024). "Our findings unravel a new interplay between M2 TAMs and gastric cancer cells in the TME and suggest a new function of MALAT1 in gastric cancer progression." (PMID 38639382, 2024). "MALAT1 competitively sequestered miR-23b-3p and attenuated the inhibitory effect of miR-23b-3p on ATG12, thereby increasing the expression of ATG12 and promoting autophagy associated chemotherapy resistance of gastric cancer (GC) cells." (PMID 36829256, 2023). "In gastric cancer, the high expression of HMGB2 predicts a poor prognosis and its expression is regulated by non-coding RNA, miRNA-23b-3p, miRNA-1297, MALAT1, and miRNA-873 to promote the proliferation, migration, and invasion of cells." (PMID 35962344, 2022). "Several of the induced lncRNAs, such as MALAT1, PVT1, and XIST, have also been shown to have specific properties in gastric cancer and were also identified as upregulated in NPC (25, –, 27)." (PMID 35435703, 2022). "MALAT1 directly binds to SOX2 mRNA, which enhances its stability so that it can have a positive effect on the regulation of stemness of gastric cancer cells." (PMID 35650297, 2022). "MiR-124-3p mimics abrogated lncRNA MALAT1 promoted EZH2 expression and gastric cancer cell proliferation and migration." (PMID 33482814, 2021). "H2 exposure drastically reduced gastric cancer growth in xenograft mouse model and inhibited EZH2 expression in cancer tissue, which was enhanced by miR-124-3p and suppressed by lncRNA MALAT1." (PMID 33482814, 2021). "LncRNA MALAT1 regulated miR-30e/ATG5 expression to modulate autophagy and apoptosis of SGC7901 gastric cancer cells and conferred resistance to cisplatin." (PMID 33482814, 2021). "H2 gas significantly inhibited gastric tumor growth in vivo and the proliferation, migration, and lncRNA MALAT1 and EZH2 expression of gastric cancer cells while upregulated miR-124-3p expression." (PMID 33482814, 2021). "To further determine the role of MALAT1 in DGP, we obtained the adjacent normal tissues from the stomach of diabetic gastric cancer patients with DGP symptoms and normal tissues from the stomach of non-diabetic gastric cancer patients without DGP symptoms." (PMID 34385927, 2021). "LncRNA MALAT1 vias VE-cadherin/β-catenin complex, ERK/MMP, and FAK/paxillin signal transduction pathway to regulate the VM formation of gastric cancer cells." (PMID 33542193, 2021). "Only 6 (H19, HCP5, LINC00511, MALAT1, OIP5-AS1 and RP11-618G20.1) out of 79 lncRNAs were significantly up-regulated in gastric cancer tissues compared to normal controls." (PMID 32742441, 2020). "MALAT1 also binds to miR-30b and increases ATG5 expression, whereas MALAT1 knockdown can suppress autophagy and enhance the chemosensitivity of gastric cancer cells." (PMID 32460771, 2020). "lncRNA MALAT1 has also been found to confer to PTX resistance through targeting miR-23b-3p and ATG12 in gastric cancer cells." (PMID 32192494, 2020). "By acting as a ceRNA for miR-23b-3p, MALAT1 suppresses miR-23b-3p-mediated ATG12 autophagy protein reduction, and induces gastric cancer cell autophagy and chemoresistance." (PMID 32174966, 2020). "A patent has been filed for gastric cancer diagnosis with HOTAIR and MALAT1 (CN105586399A), showing possible applications." (PMID 33330574, 2020). "Recently, existing research has specified that Malat1 regulates autophagy through the sponge of mir-23-3p, which targets HMGB2 and ATG12 in gastric cancer." (PMID 31425535, 2019).